EGFR (epidermal growth factor receptor)
Diseases named in the same sentence as EGFR in open-access papers (continued):
Sharing a sentence is not in itself a finding about the gene and the disease.
lung adenocarcinoma (continued). "Recently, Hsu and Togashi reported that lung adenocarcinomas in patients with EGFR mutations tend to have an invasive solid pattern at early stages and diffuse and random pulmonary metastases at advanced stages." (PMID 26332764, 2015). "The effect of EGFR tyrosine kinase inhibitors (TKIs) on EGFR-mutated lung adenocarcinoma patients after disease recurrence was investigated." (PMID 26486077, 2015). "The EGFR mutation rate in Uighur patients with lung adenocarcinoma is relatively lower than in Han patients, perhaps because of differences in race and region." (PMID 25886900, 2015). "We detected and analyzed differences in the EGFR mutation points of Uighur and Han patients with lung adenocarcinoma." (PMID 25886900, 2015). "Next, we investigated this genetic variation in 158 lung adenocarcinomas with the EGFR L858R mutation and found 14 (8.9%) patients had MLH1 V384D; available blood or non-tumor tissues from patients were also tested positive for MLH1 V384D." (PMID 25823662, 2015). "AKT activation is associated with disease progression in lung adenocarcinoma with wild-type EGFR in patients treated with gefitinib." (PMID 26160843, 2015). "Taken together, our results led us to conclude that VNR-induced EGFR dephosphorylation is associated with the anti-proliferative effect of VNR in lung adenocarcinoma cell lines harboring EGFR mutations." (PMID 25573239, 2015). "Lung adenocarcinomas have shown more driver mutations that can be successfully targeted such as EGFR, ALK, ROS1." (PMID 26371045, 2015). "In this study, based on a comprehensive analysis of a substantial number of lung adenocarcinoma samples, we characterized and determined the frequency of EGFR mutations in Polish patients (12.1%)." (PMID 25719557, 2015). "In summary, our findings demonstrate that lung adenocarcinomas harboring the EGFR-L858R mutation exhibit increased cancer cell invasive ability and enhanced MPE formation, effects mediated through ERK-dependent activation of CXCL12-CXCR4 signaling pathways." (PMID 26338423, 2015). "In the present study, we retrospectively compared the efficacy of the combination treatment of VNR + DIF with that of the standard platinum-based chemotherapy in patients with lung adenocarcinoma harboring EGFR mutations." (PMID 25573239, 2015). "To confirm the role of fulvestrant in reversing resistance to EGFR-TKIs, we enrolled one female Chinese patient with stage IV lung adenocarcinoma and an EGFR mutation." (PMID 26096604, 2015). "The discovery of activating epidermal growth factor receptor (EGFR) mutations as predictors of a response to EGFR tyrosine kinase inhibitor (TKI) therapy profoundly changed the therapeutic landscape of lung adenocarcinoma." (PMID 26018876, 2015). "Epidermal growth factor receptor tyrosine kinase inhibitors (EGFR-TKIs) are effective in some lung adenocarcinoma patients with EGFR mutations." (PMID 26268703, 2015). "Since November of 2007, the BNHI began to reimburse Gefitinib as a second-line treatment for adenocarcinoma and in June of 2011, the BNHI started to reimburse Gefitinib as a first-line treatment for lung adenocarcinoma with EGFR mutations." (PMID 26091466, 2015). "Here, we investigated the effect of EGFR TKIs on EGFR-mutated lung adenocarcinoma patients after disease recurrence." (PMID 26486077, 2015). "The IASLC/ATS/ERS lung adenocarcinoma classification system has powerful prognostic value and shows molecular correlations (such as thyroid transcription factor-1, Ki-67, EGFR/KRAS mutations)." (PMID 26318038, 2015). "In conclusion, the PFS afforded by the VNR + DIF combination treatment was significantly longer compared to that of platinum-based chemotherapy in lung adenocarcinoma patients with EGFR mutations." (PMID 25573239, 2015). "EGFR mutation frequencies in lung adenocarcinoma reported in various studies have exhibited significant variations due to ethnicity, sex and smoking status." (PMID 26332764, 2015).
lung adenocarcinoma (continued). "Around 70% of patients with lung adenocarcinoma that has activating EGFR mutations (mostly a small in-frame deletion in exon 19 and a substitution mutation L858R) display objective clinical response to EGFR-TKI treatment." (PMID 25823662, 2015). "The current studies have confirmed that EGFR TKIs had a higher efficacy in patients with lung adenocarcinoma and patients with EGFR mutations." (PMID 26285137, 2015). "This purpose of this study was to examine clinical-pathologic factors – particularly smoking and brain metastases – in EGFR mutation positive (M+) lung adenocarcinoma (ADC) to determine their impact on survival in patients treated with first line EGFR TKI." (PMID 25955322, 2015). "Now, oncogenic protein kinases inhibitors have been prevailing in lung adenocarcinoma, such as targeting epidermal growth factor receptor (EGFR) mutation or anaplastic lymphoma kinase (ALK) rearrangement." (PMID 26788508, 2015). "Accordingly, LUX-Lung 3 examined the efficacy of afatinib compared with pemetrexed and cisplatin as first-line treatment for patients with advanced lung adenocarcinoma harboring EGFR-activating mutations." (PMID 25674538, 2015). "Patients eligible for FDA approved targeted therapies (erlotinib, afatinib, crizotinib, and ceritinib) are those diagnosed with advanced stage lung adenocarcinomas with activating mutations in the EGFR gene or EML4-ALK fusions." (PMID 26603430, 2015). "The PIONEER study (NCT01185314) is a large prospective molecular epidemiology study in Asian patients with newly diagnosed advanced lung adenocarcinoma, aiming to assess their EGFR mutation status." (PMID 26599344, 2015). "The EGFR-MEK-ERK1/2 pathway has been implicated in the transcriptional regulation of CLDN2 in A549 lung adenocarcinoma cells through binding of the transcription factors, c-Fos and c-Jun, to the human CLDN2 promoter region via an AP-1 binding site." (PMID 25823815, 2015). "Nowadays, EGFR-TKIs are used as the standard first-line therapy for patients with advanced lung adenocarcinoma harboring activating EGFR mutations, and they remarkably improve the survival and quality of life in patients with these driver mutations." (PMID 25823662, 2015). "Case 1 was a 78-year-old Japanese male diagnosed with stage IB lung adenocarcinoma who was found to have two EGFR mutations, G719S and L747S." (PMID 24396447, 2014). "Clinical and epidemiologic evidence has shown that more than 50% of lung adenocarcinoma cases in Asia express the epidermal growth factor receptor (EGFR) mutation." (PMID 25105411, 2014). "ALK rearrangements and driver mutations such as EGFR and K-ras are frequently found in all types of lung adenocarcinoma." (PMID 24885886, 2014). "The LUX-LUNG 3 study, a multicenter, randomized, open-label phase III study compared afatinib with cisplatin plus pemetrexed in patients with lung adenocarcinoma, stage IIIb/IV harboring EGFR mutations." (PMID 25505694, 2014). "EGFR mutation is a validated predictive marker for response and progression-free survival when using EGFR-TKIs during first-line therapy in advanced lung adenocarcinoma." (PMID 25295103, 2014). "We also confirmed that these driver mutations lack prognostic value in lung adenocarcinoma patients who didn't receive EGFR TKI treatment, and subtypes divided by these oncogenic driver mutations don't predict significant survival difference." (PMID 25198510, 2014). "The results of this study show that lung adenocarcinoma positive for the EGFR mutation tends to increase the intensity of some VOC peaks using IMS." (PMID 25490772, 2014). "Despite good initial responses, drug resistance and disease recurrence remain major issues for lung adenocarcinoma patients with epidermal growth factor receptor (EGFR) mutations taking EGFR-tyrosine kinase inhibitors (TKI)." (PMID 25105411, 2014).
lung adenocarcinoma (continued). "We initially characterized the EGFR-mutated lung adenocarcinoma cell lines used in this study by measuring cell viability in the absence or presence of EGFR-TKIs after 72 h." (PMID 24928511, 2014). "In the validation cohort, 131 advanced lung adenocarcinoma patients with known EGFR mutation status and TTF-1 status were analyzed." (PMID 25594059, 2014). "An additional factor that must be considered is that EML4–ALK fusions were detected in only about 5% of lung adenocarcinoma, and it was mutually exclusive to other EGFR mutations and K-ras mutations." (PMID 25003505, 2014). "Our results give further support to evidence that activating EGFR mutations are an early genomic aberration in lung adenocarcinoma." (PMID 24742923, 2014). "Of the 107 lung adenocarcinoma samples, 25.2% (27/107) of tumors were found to harbor EGFR kinase domain mutations." (PMID 25198510, 2014). "Distinguished from lung squamous cell carcinoma, lung adenocarcinoma has its unique biological and clinical characteristics, such as frequent mutations of epidermal growth factor receptor and anaplastic lymphoma kinase." (PMID 24661909, 2014). "Formalin-fixed paraffin-embedded tumors from lung adenocarcinoma patients were analyzed for EGFR mutations by allele-specific PCR in the ‘pilot cohort’." (PMID 25594059, 2014). "In our series of Caucasian women with advanced adenocarcinoma of the lung EGFR mutations seem to be associated with lower benefit from first-line platinum-based CT." (PMID 25300933, 2014). "Although these molecular diagnostic markers were precise and contributed to targeted therapies, most of the studies used EGFR and K-ras mutations to classify the subtypes of lung adenocarcinoma." (PMID 25003505, 2014). "Activating EGFR mutations are detected in about 10%–17% of human lung adenocarcinoma cases, with higher percentages in women and patients with no smoking history." (PMID 24662938, 2014). "Despite significant progress in therapy of lung adenocarcinoma, all patients with EGFR mutations and ALK or ROS1 translocations receiving specific tyrosine kinase inhibitors will ultimately experience relapse." (PMID 24879454, 2014). "In Group-II analysis, 598 of 996 lung adenocarcinoma patients (60.0%) had detectable EGFR mutations." (PMID 25215536, 2014). "For example, lung adenocarcinoma patients with an epidermal growth factor receptor (EGFR) mutation or with an ELM4-ALK fusion protein have been shown to respond well to the corresponding drugs." (PMID 25364428, 2014). "Our retrospective analysis belongs to the largest reports on nationally-based lung adenocarcinoma tested for EGFR mutations." (PMID 24991207, 2014). "Mutations in the tyrosine kinase epidermal growth factor receptor (EGFR) induce oncogenic addiction in lung adenocarcinoma (LAD)." (PMID 24928511, 2014). "The independent Group-II lung adenocarcinoma patients whose EGFR mutation status determined by DS were recruited to evaluate the potential limitations of three MtS methods." (PMID 25215536, 2014). "Many evidences showed that patients with advanced lung adenocarcinomas harbor EGFR mutations, L858R missense mutations at exon 21 or deletions in exon 19 were more sensitive to the EGFR-TKI erlotinib or gefitinib." (PMID 25162713, 2014). "In previous cancer studies, association between specific CNAs and point mutations have been reported such as, for example, the relationship between EGFR mutations and copy-gains of 7p12 (which harbors EGFR gene) in lung adenocarcinomas." (PMID 24739673, 2014). "In clinical practice, TTF-1 expression combine with EGFR mutations, especially exon 21 mutation can guide clinical treatment timely for lung adenocarcinomas." (PMID 24743427, 2014). "The diagnosis was confirmed by endobronchial biopsy as T4N3M1b, stage IV lung adenocarcinoma with an epidermal growth factor receptor mutation." (PMID 25364413, 2014).
lung adenocarcinoma (continued). "Uncovering of activating mutations in tyrosine kinase domain of EGFR has led to developing and wide use of gefetinib and erlotinib, which has proven to be effective in the treatment for part of EGFR mutated lung adenocarcinomas." (PMID 25198510, 2014). "A considerable proportion of lung adenocarcinomas develop through acquisition of mutations in EGFR, KRAS, or ALK genes." (PMID 24466154, 2014). "Epidermal growth factor receptor tyrosine kinase inhibitors (EGFR-TKIs) have become first-line treatment drugs for lung adenocarcinoma patients with EGFR gene mutations." (PMID 24581168, 2014). "According to specific oncogenic driver mutations, lung adenocarcinoma is divided to molecular subtypes such as EGFR, KRAS, ALK, HER2, BRAF and so on." (PMID 25198510, 2014). "For example, EGFR mutations are more prevalent in patients with lung adenocarcinoma, and the presence of these mutations is associated with sensitivity to EGFR tyrosine kinase inhibitors." (PMID 24625834, 2014). "To confirm that this phenomenon was not limited to PC9 cell line, we transfected HCC4006, a human lung adenocarcinoma harboring an EGFR exon 19 deletion, with cDNA encoding DDX3X (HCC4006 S1, HCC4006 S2)." (PMID 25343452, 2014). "Despite good initial responses to EGFR-TKIs, most lung adenocarcinoma patients with EGFR mutations who are taking EGFR-TKIs develop resistance within 9 months." (PMID 25105411, 2014). "We retrospectively evaluated the outcomes of Caucasian women with lung adenocarcinoma, undergoing first-line platinum-based CT and subsequent salvage anti-EGFR TKI therapy, in relation to EGFR and K-Ras mutational status." (PMID 25300933, 2014). "The aim of this study is to investigate the protein expression level of Nrf2 in lung adenocarcinoma patients with EGFR gene mutations and to elucidate the correlation between Nrf2 expression and response rate of first-line EGFR-TKIs, as well as PFS and OS." (PMID 24581168, 2014). "The patient was subsequently diagnosed with advanced lung adenocarcinoma, and an EGFR mutation (in-frame deletions of E746-A750 in exon 19) was found." (PMID 25120716, 2014). "The analysis of these patients of lung adenocarcinomas indicates that TTF-1 positive expression has correlation with EGFR mutations (p<0.001), most of all for exon 21 mutation(p = 0.019),especially for those female, nonsmokers." (PMID 24743427, 2014). "Nowadays, EGFR mutational status is a well-recognized predictive factor for anti-EGFR TKIs activity and an essential tool for treatment allocation in advanced lung adenocarcinoma." (PMID 25300933, 2014). "In a study by Masahiro Seike, miR-21 was up-regulated in the lung adenocarcinoma cell line H3255, which contains an EGFR mutation and is hypersensitive to EGFR TKI AG1478." (PMID 24650032, 2014). "The existence of intratumoral mutational heterogeneity in lung adenocarcinoma has been debated since activating EGFR mutations were found to predict response to EGFR tyrosine kinase domain inhibitors." (PMID 24742923, 2014). "A previous study indicated that the most frequent gene alteration in lung adenocarcinomas in Japanese patients is the EGFR mutation, with an incidence of 38%, while the most frequent gene alteration in Caucasians is KRAS mutation, with an incidence of 30%." (PMID 25364428, 2014). "The second trial (NCT01466660) is a phase II open label study comparing gefitinib with afatinib as the front line therapy for patients with lung adenocarcinoma with EGFR mutations." (PMID 25563357, 2014). "The present study reports the case of a 30-year-old patient with stage IV lung adenocarcinoma initially harboring an EGFR mutation." (PMID 25295096, 2014). "In summary, a novel TKI, icotinib showed clinically meaningful activity in the treatment of patients with lung adenocarcinoma, especially in those patients harbouring EGFR mutations, with an acceptable adverse event profile." (PMID 24836053, 2014).
lung adenocarcinoma (continued). "The diagnosis was later confirmed as a lung adenocarcinoma by an endobronchial biopsy, with a mutated (exon 19 deletion) epidermal growth factor receptor (EGFR)." (PMID 25364413, 2014). "NSCLC has become recognized as being a heterogeneous set of diseases and, in patients with lung adenocarcinomas, epidermal growth factor receptor (EGFR) mutations are associated with response to EGFR inhibitors." (PMID 26137517, 2014). "Enzymatic EGFR inhibitors are effective for lung adenocarcinomas with somatic kinase domain EGFR mutations while, paradoxically, anti-EGFR antibodies are more effective in colon and head and neck cancers where EGFR mutations occur less frequently." (PMID 24894453, 2014). "In conclusion, our study showed that circulating miRNAs were associated with EGFR status and overall survival of lung adenocarcinoma." (PMID 24282590, 2013). "Our analyses suggest that the overall genomic and transcriptional landscape of lung adenocarcinoma is affected, but only to a minor extent, by EGFR and KRAS mutation status." (PMID 24205279, 2013). "Our results indicate that the EGFR mutation in Uighur lung adenocarcinoma patients (16.2%) is significantly lower than that in Han lung adenocarcinoma patients (45.7%)." (PMID 23425899, 2013). "All these results collectively indicate that -216G/T is associated with the pleural metastasis of lung adenocarcinoma, possibly by affecting EGFR overexpression." (PMID 24137392, 2013). "Total of 301 patients with stage Ia-IIIa resected lung adenocarcinomas whose survival had been identified were retrospectively analyzed.Their EGFR mutations were detected by real-time quantitative PCR and DNA sequencing technology together." (PMID 23601297, 2013). "For lung adenocarcinoma, EGFR mutation and ALK rearrangement testing is recommended, KRAS mutation testing is suggested by the NCCN guidelines." (PMID 27605195, 2013). "EGFR mutational analysis of lung adenocarcinoma, malignant melanoma and colorectal carcinoma – Sanger/q-PCR sequencing versus NGS." (PMID 23922754, 2013). "Somatic mutation of EGFR defines a specific subclass of lung adenocarcinomas with sensitivity to treatment with the EGFR inhibitors gefitinib or erlotinib." (PMID 24255704, 2013). "In the present study, the combined effects of metformin and gefitinib were examined in vivo in a mouse xenograft model, inoculated with a human lung adenocarcinoma cell line that possesses an activating epidermal growth factor receptor mutation." (PMID 24100792, 2013). "Together, our results suggest that the genomic and transcriptional landscape of lung adenocarcinoma is only to a minor extent determined by the mutational status of EGFR and KRAS." (PMID 24205279, 2013). "Analogous to a commonly observed event during TKI treatment of EGFR-driven lung adenocarcinomas, lapatinib application was shown to induce secondary mutations within the ERRB2 kinase domain consequently leading to TKI resistance." (PMID 23630663, 2013). "In this study, we have presented the first case to be published in the literature that describes a primary lung adenocarcinoma with peritoneal metastasis and an EGFR mutation (deletion in exon 19) (Case 1)." (PMID 24137394, 2013). "The first-line treatment for lung adenocarcinoma is generally chemotherapy involving Pemetrexed; while for patient with EGFR mutation, small molecular TKI therapy is recommended." (PMID 23576138, 2013). "Our data demonstrate that mutation-specific IHC, using optimized procedures, is a reliable prescreening test for detecting EGFR mutations in lung adenocarcinoma." (PMID 23419122, 2013). "For example, epidermal growth factor receptor (EGFR) gene mutations are often associated with well differentiated adenocarcinoma of the lung with bronchioloalveolar pattern." (PMID 23617234, 2013).